PDIA2 (protein disulfide isomerase family A member 2)
Description:
Acts as an intracellular estrogen-binding protein. May be involved in modulating cellular levels and biological functions of estrogens in the pancreas. May act as a chaperone that inhibits aggregation of misfolded proteins.
Synonyms: PDIp; PDA2; PDI; PDIR
Tractability: Antibody: UniProt predicts a signal peptide or a membrane-spanning region.
Target class: Isomerase; Enzyme
Gene: Protein-coding gene on chromosome 16 (283,152 to 287,215, forward strand). Ensembl gene ENSG00000185615.
Subcellular location: Endoplasmic reticulum lumen
Pathways (Reactome):
Developmental Biology: Developmental Lineage of Pancreatic Acinar Cells
Gene Ontology:
Molecular function: protein binding; protein-disulfide reductase activity; disulfide oxidoreductase activity; protein disulfide isomerase activity
Biological process: protein folding; protein folding in endoplasmic reticulum; protein retention in ER lumen
Cellular component: endoplasmic reticulum; endoplasmic reticulum lumen
Genetic constraint (gnomAD): Loss-of-function variants: 71 observed, 48.95 expected, observed/expected ratio (o/e) 1.45, 90% interval 1.2 to 1.76. The synonymous counts are far from expectation, so gnomAD's model fits this gene poorly and the ratio says little. Missense variants: 937 observed, 704.24 expected, observed/expected ratio (o/e) 1.33, 90% interval 1.26 to 1.4. Synonymous variants: 420 observed, 307.95 expected, observed/expected ratio (o/e) 1.36, 90% interval 1.26 to 1.48.
Homologues: Orthologues: macaque PDIA2 (92% identical), guinea pig PDIA2 (83% identical), dog PDIA2 (81% identical), mouse Pdia2 (78% identical), rat Pdia2 (78% identical), pig PDIA2 (74% identical), chimpanzee PDIA2 (57% identical), tropical clawed frog pdia2 (49% identical), zebrafish pdia2 (46% identical), Caenorhabditis elegans pdi-2 (39% identical), Drosophila melanogaster Pdi (38% identical), Caenorhabditis elegans pdi-1 (32% identical), and 9 more. Paralogues in human: P4HB (46% identical), PDILT (31% identical), PDIA4 (28% identical), PDIA3 (26% identical), TXNDC5 (21% identical), PDIA5 (20% identical), PDIA6 (19% identical), TXNDC11 (19% identical), TMX3 (17% identical), ERP44 (16% identical), ERP27 (14% identical), TMX1 (11% identical), and 1 more.
Diseases named in the same sentence as PDIA2 in open-access papers:
PDIA2 is named in the same sentence as 28 diseases in open-access papers, as found by Europe PMC text mining. Sharing a sentence is not in itself a finding about the gene and the disease. The quoted sentences say what the papers report.
colon cancer (2 papers, 2022). "Our study also suggested PDIA2 as a potential diagnostic biomarker of colon cancer." (PMID 35860571, 2022). "4PBA therapy inhibited the AOM/DSS-mediated overexpression of PDIA2 and metabolic modifications and suppressed colon cancer growth." (PMID 35860571, 2022). "A previous study reported that PDIA2 was involved in immune infiltration and predicted immune infiltration of the colon cancer tissues." (PMID 35592316, 2022). "Knockdown PDIA2 in colon cancer cells restored the metabolic imbalance and significantly repressed tumor growth in the xenograft animal model." (PMID 35860571, 2022). "To confirm the role of PDIA2 overexpression in cancer development, we next generated a subcutaneous cancer model in immunocompromised nude mice by transplanting Wt, control shRNA (C0)- and PDIA2 shRNA-transfected (C3) HT-29 colon cancer cells." (PMID 35860571, 2022). "Furthermore, immunofluorescence staining in colon cancer cells indicated PDIA2 translocation into perinuclear mitochondria by showing the merging of its staining fluorescence with that of mitochondrial probe Mito-Tracker Deep Red FM." (PMID 35860571, 2022). "In this report, we have identified ER protein PDIA2 (also called as PDIP or PDA2) for the first time as a new contributor of chronic bowel inflammation to cancerous transformation in an animal model of colon cancer." (PMID 35860571, 2022). "2: Why does PDIA2 overwhelm other PDI family members in inducing a mitochondrial defect and prompting colitis to colon cancer transformation?" (PMID 35860571, 2022). "In clinic, PDIA2 was overexpressed in colon cancer tissues rather than cancer-adjacent tissues and was related with the late stages and lymph node metastasis of colon cancer." (PMID 35860571, 2022). "Consistent with previous reports, PDIA1 and PDIA3 were overexpressed in colon cancer tissues in comparison with that in their adjacent tissues, in addition to the overexpressed PDIA2; however, no statistic changes were detected for PDIA4, PDIA5, and PDIA6 expression." (PMID 35860571, 2022).
autoimmune disease (1 paper, 2013). A disorder resulting from loss of function or tissue destruction of an organ or multiple organs, arising from humoral or cellular immune responses of the individual to their own tissue constituents. "Further studies are required to disclose whether autoantibody to Pdia2 may also play a role in human gastritis and/or pancreatitis, or other organ-specific autoimmune diseases." (PMID 23991207, 2013).
autoimmune gastritis (1 paper, 2013). Inflammation of the body fundic mucosa of the stomach. "Although many kinds of tissue antigens could be the target antigens in human autoimmune pancreatitis, the anti-Pdia2 antibody identified in this study present the evidence that the autoantibody could serve as an important autoantibody in autoimmune gastritis and/or pancreatitis, at least in mice." (PMID 23991207, 2013).
Autoimmunity (1 paper, 2013). The occurrence of an immune reaction against the organism's own cells or tissues. "The production of anti-Pdia2 autoantibody correlated well with the progression of autoimmunity as revealed by the infiltration of lymphocytes in the pancreas, stomach, liver and other internal organs in accordance with aging." (PMID 23991207, 2013).
breast carcinoma (1 paper, 2020). "First, some of the variants we identified (eg, PDIA2 p.R148*) are so rare in the general population that they would require very large case‐control populations to assess their association with breast cancer." (PMID 32383162, 2020).
Chronic colitis (1 paper, 2022). A chronic inflammatory disease of the large intestine (colon, cecum and rectum). "5: Does the PDIA2-asociated mechanism in the malignant transformation of chronic colitis apply to other types of inflammation to cancerous transformation?" (PMID 35860571, 2022). "Persistent ER stress reprograms the metabolism to promote the malignant transformation of chronic colitis; PDIA2 serves as a molecule linker between ER stress and metabolic reprogramming." (PMID 35860571, 2022).
colitis (1 paper, 2025). Inflammation of the colon. "In vivo, administration of 4‐PBA in an azoxymethane/dextran sulfate sodium (AOM/DSS) mouse model of colitis‐associated colorectal cancer led to the suppression of PDIA2 overexpression, restoration of metabolic homeostasis, and a marked reduction in tumor burden." (PMID 40953838, 2025).
lymph node metastasis (1 paper, 2022). "Over-expression of PDIA2 was highly related with late stages (T3 and T4) and lymph node metastasis (N1 and N2)." (PMID 35860571, 2022).
neuroblastoma (1 paper, 2013). Neuroblastoma (NB) is the most common solid, extracranial childhood tumor. "PDIA2 is upregulated in SH-SY5Y human neuroblastoma treated with either 1-methy-4-phenyl-pyridinium (MPP+) or proteasome inhibitor lactacystin while immunoreactivity to PDIA2 has also been detected in LB in postmortem brains of PD patients." (PMID 24348565, 2013).
ovarian carcinoma (1 paper, 2021). A malignant neoplasm originating from the surface ovarian epithelium. "PDIA2 is a critical prognostic marker that plays an important role in the drug-resistance phenotype in ovarian carcinoma." (PMID 34635181, 2021).
pancreatic cancer (1 paper, 2023). "The protein products from AGR2, CEAMAN6, GNMT, PDIA2, POSTN, RBPJL and S100P have been reported as potential diagnostic and prognostic biomarkers for pancreatic cancer or have demonstrated to be involved in either pancreatic cancer, initiation, migration, invasion, metastasis, or chemoresistance." (PMID 36812168, 2023).
pancreatic tumor (1 paper, 2023). "Using this approach and verifying the data using individual gene expression data, we found that AGR2, CEACAM6, GNMT, PDIA2, POSTN, RBPJL, and S100P are upregulated in pancreatic tumor tissue as compared to non-tumor tissue from Black and White patients." (PMID 36812168, 2023).
vitiligo (1 paper, 2023). Generalized well circumscribed patches of leukoderma that are generally distributed over symmetric body locations and is due to autoimmune destruction of melanocytes. "Linkage analysis for a four generations Chinese family identified 16p13.3p13.2 as the susceptibility locus of vitiligo, whole exome sequencing then identified PDIA2 as the new candidate gene." (PMID 37799362, 2023).
tumor (8 papers, 2020 to 2025). "Although the maximal OCR of PDIA2- knockdown tumor cells was still higher than that of Wt tumor cells, their ECAR became comparable." (PMID 35860571, 2022). "To confirm this possibility, we compared the differences in mitochondrial respiration and glycolysis between Wt and PDIA2-knockdown tumor cells using Seahorse analysis." (PMID 35860571, 2022). "Since then, tumors from both Wt and control RNAi cells continued to grow fast in parallel, the tumor size reached 181.4 ± 23.9 mm2 and 164.8 ± 6.9 mm2, respectively, at day 27 after cell transplantation, in contrast to the tumor size 101.6 ± 11.5 mm2 from the PDIA2-knockdown cells." (PMID 35860571, 2022). "The downexpression of PDIA2 restored energetic homeostasis and inhibited tumor growth." (PMID 35860571, 2022). "Subcutaneous cancers became visible at 2 weeks after the transplantation of all types of cells; the tumor sizes developed from Wt (77.0 ± 14.7 mm2) and control RNAi cells (65.9 ± 6.7 mm2) were comparable but were over 2-fold larger than those developed from PDIA2-knockdown cells (33.3 ± 2.9 mm2)." (PMID 35860571, 2022). "In addition, PDIA2 overexpression is positively related to primary tumor grading." (PMID 35860571, 2022). "High genomic alterations in zesto lesions were inversely correlated with putative tumor suppressor genes (MTUS2, DLGAP3, RTN1, CRLF1, SLC12A5, and PDIA2) and positively correlated with APOBEC mutagenesis (APOBEC3C, APOBEC3G, APOBEC3B, and APOBEC3F) and hypoxia-related gene signatures." (PMID 40319462, 2025). "However, we deem that PDIA2, even though important, is not the only factor of ER stress in promoting a cancerous transformation of inflammation; this is evidenced by the fact that the repression of PDIA2 only abates but does not prevent tumor development from inflammatory ER stress." (PMID 35860571, 2022).
cancer (2 papers, 2022 to 2025). A tumor composed of atypical neoplastic, often pleomorphic cells that invade other tissues. "Thus, the knockdown expression of PDIA2 and its associated metabolic reprogramming inhibit cancer cell growth and defer fast cancer development, particularly in the early stage, highlighting a prompting role of PDIA2 in inflammation to cancerous transformation." (PMID 35860571, 2022). "Both cancer and adjacent tissues expressed PDIA2 protein, and cancer tissues expressed approximately 2.8-fold more PDIA2 protein than their adjacent tissues." (PMID 35860571, 2022). "Cancer tissues expressed approximately 2.8-fold more PDIA2 protein than adjacent colon tissues in 61 of 74 pairs of tissues." (PMID 35860571, 2022). "To determine if PDIA2 overexpression affects the proliferation of cancer cells, we compared the cell growth rate of Wt, control shRNA (C0)- and PDIA2 shRNA (C3)-transfected HT-29 cells by the CCK8 assay." (PMID 35860571, 2022). "In our chronic bowel inflammation to the CRC animal model, PDIA2, standing out of other PDIs, significantly upregulated from a chronic inflammation status to cancer development." (PMID 35860571, 2022). "PDIA2 expression was upregulated in cancer cells in response to ER stress." (PMID 35860571, 2022). "Hyperglycolysis is a typical signature of both inflammatory and cancer cells; we then firstly compared the real-time kinetics of glycolysis by measuring the extracellular acidification rate (ECAR) in control and PDIA2-knockdown cells using the glycolytic stress assay." (PMID 35860571, 2022).
PDIA2 also shares sentences with these, for which no sentence is quoted: Parkinson disease (2 papers); adenosquamous carcinoma (1); autoimmune pancreatitis (1); Bicuspid aortic valve (1); brain cancer (1); chronic hepatitis (1); colorectal cancer (1); dyslipidemia (1); gallbladder adenocarcinoma (1); gastritis (1); glioma (1); melanoma (1); pancreatitis (1).